CDX2 (caudal type homeobox 2)
Diseases named in the same sentence as CDX2 in open-access papers (continued):
Sharing a sentence is not in itself a finding about the gene and the disease.
colorectal cancer (continued). "However, due to the fact that non-specific expression of CDX2 may lead to the generation of side effects, regulated colorectal cancer cell-specific expression of CDX2 is necessary." (PMID 25847407, 2015). "The cutaneous metastases from colorectal carcinoma were adenocarcinomas and expressed both CK20 and CDX2." (PMID 40407482, 2025). "Among the syntenic blocks between these regions, CDX2, CDK8, GSX1, and PDX1 are among candidate colorectal carcinoma and/or cancer driver genes affected by these recurrently gained chrs between human and mouse." (PMID 41051921, 2025). "All PDOs expressed major colorectal cancer specific markers, such as CK AE1/AE3, CK20 and CDX2 as the corresponding clinical samples." (PMID 38698446, 2024). "In terms of direct targets, SMYD2 regulates the level of H3K36me2 on Mex-3 RNA-binding family member A (MEX3A), thereby controlling the growth of colorectal cancer by regulating the target of MEX3A, namely, caudal type homeobox 2 (CDX2)." (PMID 39482529, 2024). "Expression of the CDX2 transcription factor, the main determinant of the epithelial sub-type, has been previously shown to be prognostic in stage II and III colorectal cancers." (PMID 39452477, 2024). "CK20 and CDX2 are highly specific markers for colorectal carcinomas, with CK20 expressed in 70%–100% of cases and CDX2 in 97%." (PMID 39052015, 2024). "CDX2 is frequently methylated in human ESCC, but unmethylated in colorectal cancer and esophageal adenocarcinoma." (PMID 36461092, 2022). "Studies have confirmed that Caudal Type Homeobox 2 (CDX2) plays a tumor suppressor role in colorectal cancer (CRC) and as a prognostic and predictive marker for colorectal cancer." (PMID 36277982, 2022). "Consistent with our findings, an inverse correlation between SOX2 and CDX2 was recently reported in gastric cancer and colorectal cancer, suggesting the mutual suppression of the expression of SOX2 and CDX2." (PMID 35602937, 2022). "At the same time, CDX-2 (+) and SATB2 (+) was discussed as combination marker to discriminate colorectal carcinoma from other primary carcinoma, and 19% of gastrointestinal adenocarcinoma with CK7 (+) /CDX-2 (+) /SATB2 (+) showed primary colorectal cancer." (PMID 36463302, 2022). "We applied this method for five biomarkers (CDX2, SOX2, SOX9, E-cadherin, and β-catenin) using tissue microarrays of a Norwegian unselected series of primary colorectal cancer." (PMID 31641225, 2020). "We performed DIA of fluorescence-based mIHC stains of CDX2, SOX2, SOX9, E-cadherin, and β-catenin in colorectal cancer samples arranged in TMAs, and compared with previous visually scored chromogenic IHC stains of the same series." (PMID 31641225, 2020). "Both of PEAC and MCAC can be present with a morphology of colorectal carcinoma, and CK20, CDX2 and MUC2 can be immunohistochemically positive in both of them." (PMID 32429938, 2020). "These xenotransplants were analyzed by a certified pathologist who confirmed that BRCA1-KO fibroblasts displayed colorectal cancer phenotype as judged by the expression of specific markers (CK20, CEA, CDX2, AE1/AE3)." (PMID 31200749, 2019). "In the authors' opinion, colorectal cancer should be tested for MMR status first, and CDX2 testing should be considered only when the tumour is pMMR." (PMID 30511046, 2018). "In colorectal cancer Caco-2 cells, the activity of the ELMO3 promoter can be regulated by caudal-related homeobox transcription factor 2 (CDX2), which interacts with SP1." (PMID 30345300, 2018). "The tumors generated with cells treated with cases E, G, H and I (colorectal cancer) were negative for CK7 but they all stained positive for CEA, CK20, CDX-2 and AE1/AE3, which are universal markers of colorectal cancer." (PMID 27179759, 2016). "MS4A12 is elevated in colorectal cancer, but down-regulated in our PMP samples despite being a known CDX2 transcriptional target, often up-regulated in PMP." (PMID 25929336, 2015).
colorectal cancer (continued). "Inverse correlation between the expression of caudal type homeobox 2 (CDX2), a homeodomain protein, and HIF-1α is observed in colorectal cancer samples." (PMID 23241400, 2012). "In contrast to previous results that have shown worse prognoses for stage II and III CDX2-negative colorectal cancers compared with CDX2-positive cancers, the current analysis did not disclose significant differences in survival outcomes." (PMID 39452477, 2024). "Notably, CDX2 overexpression suppressed EMT markers, highlighting its role in inhibiting colorectal cancer cell viability, invasion, and metastasis." (PMID 39328205, 2024). "Mutations in the related NRAS gene were observed in 7% of non-CDX2-suppressed colorectal cancers and in no cases of the CDX2-suppressed group (Fisher’s exact test p = 0.02)." (PMID 39452477, 2024). "The most frequent copy number alteration in colorectal cancer, amplification at locus 20q11, was observed in 12.5% to 12.9% of non-CDX2-suppressed cancers, but in none of the CDX2-suppressed cases (Fisher’s exact test p = 0.0004)." (PMID 39452477, 2024). "The mutual exclusivity of RNF43 and APC mutations observed in the current report was previously reported in colorectal cancer in a report that did not examine CDX2 suppression." (PMID 39452477, 2024). "In the current investigation, colorectal cancers with suppressed CDX2 mRNA expression are examined for concomitant molecular alterations and clinical characteristics and compared with colorectal cancers with no CDX2 suppression." (PMID 39452477, 2024). "An exception to this immunohistochemical pattern is represented by the enteric-type lung adenocarcinoma, which may have the same immunohistochemical profile of colorectal carcinomas, showing positivity for CK20 and CDX2." (PMID 36835963, 2023). "CDX2 downregulation in MSI‐H and CIMP‐H colorectal carcinomas may also be due to methylation of the promoter region, but it may occur later than SATB2 for unknown reasons." (PMID 37036163, 2023). "A recent systematic review and meta-analysis revealed that CDX2 expression reduced mortality, with a 50% reduction in death compared to patients with colorectal cancer with poor or no CDX2 expression." (PMID 35323316, 2022). "CDX2 was regarded as a tumor suppressor in ESCC and an oncogene in colorectal cancer." (PMID 36461092, 2022). "While the diagnosis of colorectal cancer benefits from relatively sensitive and specific biomarkers indicating a CDX2 and CK7-/CK20+ phenotype, some colorectal cancers lack such typical molecular characteristics as exemplified by our samples from colorectal cancer metastases." (PMID 33852640, 2021). "Although CDX2 functions in cancer invasion and metastasis, fewer studies focus on the role of CDX2 during the induction of epithelial–mesenchymal transition (EMT) in colorectal cancer (CRC)." (PMID 33239678, 2021). "CDX-2 is a marker of gastrointestinal tumors, especially colorectal cancer, while urothelial tumors do not express CDX-2, which can be used to differentiate adenocarcinomas from the gastrointestinal tract." (PMID 32664169, 2020). "By analyzing both serial stains and the multiplex staining of CDX2 and SOX2 we confirmed their inverse relationship in colorectal cancer; however, the inverse correlation was considerably stronger for DIA (Spearman’s rho test, Allred r = −0.16; DIA r = −0.51; n = 357)." (PMID 31641225, 2020). "A lack of caudal-type homeobox transcription factor 2 (CDX2) protein expression has been proposed as a prognostic biomarker for colorectal cancer (CRC)." (PMID 31783700, 2019).
colorectal cancer (continued). "CDX2 and polyclonal carcinoembryonic antigen (p-CEA) may mark both colorectal carcinomas with plasmacytoid morphology and PUCs but uroplakin is positive for PUCs only." (PMID 31205468, 2019). "Both ITACs and colorectal carcinomas express CK20, CDX-2, villin and MUC2, but the expression of CK7 in a tumor may be suggestive of ITAC." (PMID 28321774, 2017). "Therefore, the past medical history of colorectal carcinoma and application of IHC studies of CK7, CK20, and CDX2 are helpful to achieve the correct diagnosis and management." (PMID 27429820, 2016). "To confirm these findings in a more physiologic setting, we used retroviral transduction to over-express either EGFP, CDX2, or CDX2/AS in HT29 and SW480 colorectal cancer cells that express endogenous CDX2 and CDX2/AS and compared expression of endogenous GUCY2C transcripts." (PMID 25101906, 2014). "CDX2 does not appear to be a sensitive marker for poorly differentiated colorectal carcinomas, and it is not a completely specific marker." (PMID 25299496, 2014). "CDX2, a marker expressed in over 90% of colorectal cancers, is absent in mammary glands." (PMID 41458856, 2025). "About 10% of colorectal cancers were CDX2-negative and had a worse prognosis." (PMID 39452477, 2024). "Additionally, it is essential to acknowledge the challenge posed by the lack of standardisation of CDX2 staining, which makes data interpretation between studies and the clinical use of this biomarker in colorectal cancer inherently complex." (PMID 39201360, 2024). "However, CDX2 can work together with beta-catenin to regulate tight junctions via promoting the expressions of claudin-1, which leads to an increase in invasion and EMT in colorectal cancer cells." (PMID 36277982, 2022). "However, neither villin nor CDX2 is related to none of the clinical and pathological parameters in colorectal cancer." (PMID 33036298, 2020). "The tumor markers CDX2, beta-catenin and Wnt3a were not good instruments to assessthe chance of disease progression or the possibility of evolution to death in thecontext of colorectal cancer." (PMID 33331430, 2020). "Digital image analysis (DIA) of multiplex fluorescence-based immunohistochemistry and visual chromogenic evaluation of CDX2, SOX2, SOX9, E-cadherin, and β-catenin in colorectal cancer are comparable, recognizing prognostic value of CDX2 and negative correlation with SOX2." (PMID 31641225, 2020). "However, the prognostic effect of CDX2 expression for overall survival in dMMR colorectal cancer was not independent of stage." (PMID 30511046, 2018). "However, whether dysregulated CDX2 levels correlate with ST14 and SPINT1 in clinical colorectal cancer specimen needs to be clarified." (PMID 30087389, 2018). "CDX2 is absent in 183 out of 621 colorectal cancers from patient specimens." (PMID 28835570, 2017). "The in vivo experiments were performed over a loner time-period, indicating that the inhibitory effects of CDX2 on colorectal cancer were time-dependent and the short-term effects were not significant, but CDX2 may inhibit tumor growth over a longer duration." (PMID 26005051, 2015). "Colorectal cancer cases that are negative for CDX2 expression tend to be poorly differentiated tumours, and consistent with this finding, we observed that whereas 100% of well-differentiated tumours were CDX2 positive, only 58% of poorly differentiated tumours were CDX2 positive." (PMID 19935793, 2010). "Finally, the integration of CDX2 with molecular biomarkers such as MSI, RAS, BRAF, or SATB2 may lead to the development of comprehensive prognostic and predictive models, supporting a more personalized therapeutic approach in colorectal cancer." (PMID 41388313, 2025).
colorectal cancer (continued). "This study describes a primary cutaneous PPD patient CDX-2+/CK20+/CK7- without invasion of the dermis and no associated colorectal carcinoma effectively treated using topical Imiquimod therapy, suggesting that Imiquimod might potentially be considered as a first-line treatment for PPD." (PMID 30253739, 2018). "Immunohistochemical staining showed that the tumoroids from all the groups were positive for β‐Catenin, CDX‐2, CK20, and E‐Cadherin, and negative for MUC‐2, which were the featured markers of colorectal cancers, as shown in the Protein Atlas database." (PMID 40611658, 2025). "Histopathology and immunohistochemistry (CK7, CK20, CDX2, SATB2, Arginase-1) confirmed that the intestinal lesions were metastases from gastric cancer rather than synchronous primary colorectal cancers." (PMID 41159019, 2025). "Immunostaining findings also suggested that this tumor was not a metastasis of urothelial carcinoma or colorectal cancer, as urothelial carcinoma is positive for CK7, CK20, and p63, and colorectal cancer is frequently positive for CK20 and CDX2." (PMID 39310547, 2024). "As mentioned in the previous review, colorectal carcinoma is positive for CK20 and CDX2 and negative for breast markers ER and PR in greater than 90% of cases." (PMID 35444939, 2022). "Interestingly, six SBAs (two CD-SBAs and four Spo-SBAs) displayed a full colorectal carcinoma (CRC)-like immunoprofile (CK7−/CK20+/CDX2+/AMACR+/SATB2+); none of them was a CrD-SBA." (PMID 33228145, 2020). "Immunohistochemical reevaluation showed the cervical lymph node biopsy specimen to be positive for CDX2 and CK20 and negative for CK7 expression, leading us to suspect the presence of a primary colorectal cancer." (PMID 21595976, 2011). "In particular, a pattern of positive CDX2 or CK20 expression and negative CK7 expression is indicative of primary colorectal cancer." (PMID 21595976, 2011). "A CDX-2 and CK20-positive and CK7-negative profile is indicative of digestive tract adenocarcinoma, particularly colorectal carcinoma, and is rare in urothelial tumors, which normally express CK7 alone or together with CK203 and do not express CDX-2." (PMID 18094900, 2007). "Moreover, cells treated with exosomes derived from the sera of patients with colorectal cancer gave rise to tumors that displayed epithelial features typical of colorectal adenocarcinomas (negative for CK7, and positive for CEA, CK20, CDX-2 and AE1/AE3)." (PMID 28854931, 2017). "Moreover, the specificity of IHC is not always useful for distinction: e.g. TTF1 CK7, CDX2 and CK20 do not have any distinctive capacity between primary intestinal carcinoma from the lung and a metastasis from a colorectal carcinoma, as the IHC pattern is the same: TTF1-, CK7-, CDX2+ and CK20+." (PMID 31618260, 2019). "Tumors, generated with colorectal cancer sera-treated cells, displayed epithelial features typical of colorectal adenocarcinomas, as they all stained negative for CK7, and expressed CEA, CK20, CDX-2 and AE1/AE3, which are universal markers of colorectal cancer." (PMID 28854931, 2017).
colon carcinoma (143 papers, 2001 to 2026). "High CDX2 expression frequently indicates better survival in stage II-III colon cancer; nevertheless, it is linked to decreased systemic chemotherapy response rates." (PMID 41820294, 2026). "FBXW7 and GSK3β overexpression reduces CDX2 levels and function, causing growth arrest in colon cancer cells; disruption of both CDX2 phosphodegrons prevents FBXW7-mediated degradation." (PMID 41373479, 2025). "In vitro study of FBXW7-mediated CDX2 ubiquitination using coimmunoprecipitation and phosphodegron mutations in colon cancer and HEK293T cells." (PMID 41373479, 2025). "Organoids derived from colonic tumors carrying Cdx1 and Cdx2 mutations exhibited increased proliferation and elevated Lgr5 expression levels." (PMID 40399276, 2025). "The studies reveal that the transcriptional programs driven by key lineage specification TFs, such as CDX2, are critical determinants of tissue-site-specific susceptibility to colon cancer development by cancer driver mutations." (PMID 38360902, 2024). "Another report pinpointed to the association of CDX2 suppression with right colon cancers and BRAF mutations." (PMID 39452477, 2024). "Analyses of the in vivo human colon cancer data show that the transcriptional programs in the Cdx2-deficient organoid model recapitulate those in proximal human colon cancers." (PMID 38360902, 2024). "Genes encoding for several receptor tyrosine kinases were mutated in a significant minority of CDX2-suppressed colon cancers, while the prevalence of such mutations was lower in most of these genes in the group with non-CDX2-suppressed colon cancers." (PMID 39452477, 2024). "Amongst the CDX2-correlated genes from human colon cancers, those downregulated in proximal organoids with Cdx2 loss included the key epithelial regulatory genes, such as Hnf4A, Satb2, and Vil1." (PMID 38360902, 2024). "Among MMR-associated genes, MSH6 and PMS2 were significantly more frequently mutated in CDX2-suppressed colon cancers, and the same was true for mutations in the proofreading polymerases POLE and POLD1 genes." (PMID 39452477, 2024). "These associations match with observations that colon cancers with low CDX2 expression predominantly occur in the proximal side of the colon (p-val < 0.001) and/or in the context of BRAF mutation (p-val < 0.001) 19,46." (PMID 38360902, 2024). "Mouse polyps and colon cancers from participants carrying the HNF1AA98V variant exhibited reduced CDX2 and elevated β-catenin proteins." (PMID 37219942, 2023). "Their conclusion was that identifying a group of stage II colon cancer patients for targeted chemotherapy based on CDX2 expression loss was a cost-effective strategy." (PMID 37325467, 2023). "The intestinal restricted transcription factor CDX2 has been implicated in colon cancer, where it functions as a tumor suppressor." (PMID 37627195, 2023). "Recent level 1 evidence highlights the association of a loss of CDX2 expression with worse prognostication in colon cancer (reduced OS and DFS)." (PMID 35323316, 2022). "Brummer's group has demonstrated a few years ago a positive correlation between BRAF mutation and low level of Cdx2 expression in colon carcinoma." (PMID 32426274, 2020). "As a homeotic transcriptional factor, CDX2 was poorly expressed in colon cancer and associated with invasion and metastasis of cells." (PMID 31938021, 2020). "The downregulation of CDX2, and thereby loss of intestinal identity, has been suggested to be a precursor for metastatic colon cancer to perform epithelial-to-mesenchyme transition (EMT)." (PMID 32408894, 2020). "Loss of CDX2 expression has recently emerged as a biomarker for colon cancers arising via the serrated pathway, often coinciding with activated BRAF mutations." (PMID 31739541, 2019). "Loss of CDX2 has consequently been linked to increased cell migration and malignant transformation, often acting as a tumour suppressor in colon cancer, while in other settings related to an oncogenic role." (PMID 30425348, 2018).